ERBB2 (erb-b2 receptor tyrosine kinase 2)
Diseases named in the same sentence as ERBB2 in open-access papers (continued):
Sharing a sentence is not in itself a finding about the gene and the disease.
tumor (continued). "Although ERBB2-enriched and triple-negative tumor cells have low expression of hormonal receptors, exogenous hormones may play a role in receptor-negative tumor growth through hormone-mediated and hormone-independent pathways." (PMID 40622713, 2025). "Third, NRG1 is a non-selective agonist of the ERBB system, binding to both ERBB3 and ERBB4 receptors, and thus it may activate ERBB3 receptors in ERBB2-overexpressing tumor cells, thereby enhancing the formation of ERBB3/ERBB2 complexes, which could induce or accelerate cancer growth." (PMID 39794341, 2025). "Interestingly, no ERBB2 gene alterations were detected in tumor tissue, despite positive IHC evaluation." (PMID 41357601, 2025). "Notably, responses were observed in patients with different mutation domains and even in those without ErbB2 overexpression, suggesting a pan-tumor applicability for ErbB2-targeted therapies." (PMID 39908697, 2025). "While survival outcomes for Black women improved among all tumor subtypes when GCC was given, racial and ethnic disparities in survival outcomes persisted among patients with hormone receptor–positive/ERBB2-negative and hormone receptor–positive/ERBB2-positive subtypes." (PMID 40009385, 2025). "IHC detects the HER2 protein on a tumour’s cell surface, providing a measure of overexpression, while ISH, including fluorescence (FISH) and chromogenic (CISH) approaches, identifies gene amplification by quantifying the ERBB2 copy numbers relative to chromosome 17." (PMID 41463236, 2025). "Furthermore, tumor content LoD studies for MSI and TMB found reliable detection of these biomarkers at 20% cutoff, which exceeded the tumor content LoD for other alterations (15% for ERBB2 CNAs, 10.5% for all SNVs and INDELs, and 12.0% for CDx variants)." (PMID 40804002, 2025). "This difference is relatively small compared to MCT4, suggesting that ERBB2 expression alone may not be crucial in distinguishing between normal and tumor tissues." (PMID 40966256, 2025). "These genes, including ERBB2, CCNA1, FOXC2, LEFTY2, VTN, ACKR3, and PTGS2, are involved in key processes like apoptosis, epithelial–mesenchymal transition, angiogenesis, response to hypoxia, and KRAS signaling pathways, which are crucial for tumor virulence and the spread of metastases." (PMID 39000413, 2024). "However, it is also plausible that the pretreatment biopsies of these cases missed the region of the tumor with ERBB2-non-amplified cells." (PMID 38300710, 2024). "This CD19-4D5-fused scFv molecule potentiates CD19 CAR T cells to target ErbB2+ cancer cells and repress tumor development by displaying a 100-fold greater selectivity toward cancerous cells than healthy fibroblasts, which was not seen in ErbB2 CAR T cells alone (without scFv fusion)." (PMID 39156005, 2024). "As the effects of anti-ErbB2 mAb therapy are also mediated by the immune system, through mechanisms including antibody-dependent cellular cytotoxicity (ADCC), we investigated whether modulating FA metabolism affected anti-tumor immune responses in our model." (PMID 39097623, 2024). "While not definitive, our findings could suggest that her tumor possibly diverged phylogenetically to form these distinct subpopulations based on ERBB2 and NF1 copy number status." (PMID 39069534, 2024). "Tumor size was selected in the luminal ERBB2-negative cohort but not in the ILC subgroup." (PMID 39320882, 2024). "Among these genes are ERBB2, CCNA1, FOXC2, LEFTY2, VTN, ACKR3, and PTGS2, which influence processes such as apoptosis, epithelial–mesenchymal transition, angiogenesis, hypoxia responses, and KRAS signaling pathways, all vital for tumor aggressiveness and metastatic spread." (PMID 39000413, 2024). "The importance of Bcl3 in maintaining tumour cell survival in the absence of exogenous stress inducers, however, remains unclear, with transgenic ErbB2 and triple-negative mouse models showing little effect on primary tumour growth following Bcl3 inhibition." (PMID 38255248, 2024).
tumor (continued). "Moreover, tumor gene expression assays demonstrated overrepresentation of aggressive non–luminal A subtypes, which accounted for most tumors in the HR-positive/ERBB2-negative subgroup." (PMID 39652347, 2024). "Two target antigens (ERBB2 and TROP2) were lineage-specific markers of two out of above approved ADCs—Trastuzumab deruxtecan, and Sacituzumab govitecan, which have consistently high expression across the BCa tumor population than normal samples in the TCGA-BLCA." (PMID 37124622, 2023). "As expected, patients in cluster A had higher immune cytolytic activity or CYT scores compared to those in cluster B. Disease stage, tumor grade, age at diagnosis, PR status, and ERBB2 (HER2) overexpression were not significantly different between the two cell clusters." (PMID 37923775, 2023). "Of interest, six proteins (FOXA1, ERBB2, MAPT, NAT1, PHGDH, KRT5) and one protein (PHGDH) overlapped between PAM50 and the differentially expressed proteins between basal-like and luminal-like subtypes in microdissected tumor epithelium and stroma, respectively." (PMID 37349288, 2023). "Furthermore, the serum ERBB2 level was demonstrated to be an important prognostic factor in predicting recurrence and survival, independent of tumor size and stage." (PMID 37174100, 2023). "However, it would be challenging to draw definitive conclusions without confirming the presence of ERBB2 amplification in corresponding tumor cells." (PMID 37336919, 2023). "Finally, immunohistochemical staining revealed enhanced HER2/ERBB2 levels in 4/5 PDO (ranging from 1+ to 3+ on IHC scoring), where in all cases the matched primary tumours were HER2 negative (0 on IHC scoring)." (PMID 37973922, 2023). "However, we identified a small triple positive (ERBB2 + /ESR1 + /PGR + (HER2 + /ER + /PR +)) DCIS region located in proximity to adipocytes which consisted of a predominantly DCIS #2 tumor epithelium without a KRT15+ myoepithelial cell layer." (PMID 38114474, 2023). "However, ERBB2 had an opposite correlation within ICCLE-BRCA (p = 0.003), suggesting potential aspects of cell line-specific variation may mask tumor sample effects." (PMID 36797360, 2023). "Taken together, we have validated in vivo that the engineered destabilized 3’UTR of ERBB2 significantly reduced the tumor volume in a deadly drug-resistant tumor model with no abnormal blood, liver, kidney, bone, pancreas, gall bladder, and electrolyte imbalance." (PMID 37359373, 2023). "ERBB2-mutant tumors have a higher microsatellite instability (MSI) and tumor mutation burden (TMB) than ERBB2 non-mutant tumors, suggesting that immune checkpoint inhibitors may be useful against ERBB2-mutant tumors." (PMID 37754252, 2023). "If ctDNA reveals ERBB2 CNG discordant from a prior HER2-negative tissue IHC/FISH, it may prompt consideration of a new biopsy and/or use of HER2 therapy as the discordance may be a result of HER2 heterogeneity or tumor evolution rather than assay variability." (PMID 35126865, 2022). "Tumor-normal and inter-tumor analyses of protein expression data highlighted multiple aberrantly-expressed protein targets in key signaling pathways, including PDGFRB, CDK6, ERBB2, and EGFR whose protein overexpression in HCC tumors are also validated by IHC data from the Human Pathology Atlas." (PMID 35433463, 2022). "Moreover, it is a novel finding that the expression levels of ERBB2 were significantly correlated to the markers of the immune cells in the PTC tissues, suggesting that ERB2 may play a crucial role in regulating the tumor-immunoenvironment." (PMID 36437939, 2022).
tumor (continued). "Interestingly, in this patient, ERBB2 copy number amplification was detected on a single CTC but not on bulk tumor analysis." (PMID 35790747, 2022). "Interestingly, in the presence of tumour microenvironmental cytokines, Erbb2 expression levels were not affected by the treatment with the PI3K inhibitor." (PMID 33436496, 2022). "Hence, KSTAR predictions of EGFR and ERBB2 basal activity correspond with lapatinib response, including the surprising result of a HER2-negative tumor responding to HER2-specific therapy." (PMID 35879309, 2022). "In addition to HER2 overexpression, genetic mutations affecting the extracellular, transmembrane, and kinase domains of ERBB2 have been reported as alternative mechanisms of HER2 activation in various solid tumors and affect tumor biology and treatment response." (PMID 36686783, 2022). "Given the increasing access to and utilization of tumor tissue and ctDNA NGS in advanced malignancies, we aimed to better understand how ERBB2 copy number gains (CNG) by commercial NGS platforms of tissue or blood predict for HER2-positivity by the ‘gold-standard’ of IHC and FISH assays." (PMID 35126865, 2022). "Of note, our data showed that MEK inhibition-based triplets were able to kill CR-CSCs in the presence of cytokines released by CAFs and to induce tumour regression in all CR-CSC-based xenografts tested, regardless of the mutational status and Erbb2 amplification." (PMID 33436496, 2022). "Additionally, IPO7 could positively modulate the ERBB2, and knockdown of IPO7 inhibited tumor growth and lung metastasis in vivo." (PMID 35588577, 2022). "Furthermore, we compared the tumor mutational burden (TMB) as well as CD8+ T cell, CD4+ T cell, and Treg immune infiltration levels between ERBB2-mutated BC and ERBB2 non-mutated BC via in silico analysis." (PMID 34257600, 2021). "Immunohistochemical markers for tumor cell surface or plasma, as well as for growth in this context are estrogen receptor, progesterone receptor, human epidermal growth factor receptor-2 (ERBB2/ HER-2) and epidermal growth factor receptor, cytokeratin 5 and/or nuclear protein Ki67 expression." (PMID 33526060, 2021). "Machine learning (ML) algorithms can predict the amplification of ERBB2 based on tumor morphological features, but it is not known whether ML-derived features can predict survival and efficacy of anti-ERBB2 treatment." (PMID 33597560, 2021). "Notably, intrapatient concordance was also found for the clinically relevant target genes ERBB2 and EGFR, including in comparison with the primary tumor of one patient with ERBB2 amplification (9 additional copies in the primary and 17 and 18 additional copies in the two metastases)." (PMID 33325154, 2021). "Nevertheless, retargeting by ErbB2-targeted CAR-expressing NK cell or high affinity FcR transgenic NK cells plus monoclonal antibody Herceptin (ADCC) provides signals necessary to achieve granule polarization and tumor cell lysis, thereby circumventing tumor cell resistance." (PMID 34071188, 2021). "To determine whether ErbB2 degradation triggered by DEPTOR knockdown plays a causal role in the inhibition of cell proliferation and survival, we ectopically expressed ErbB2-YVMA, a constitutively active ErbB2 A775-G776insYVMA mutant from human tumor patients 23, in DEPTOR-depleted cells." (PMID 33995662, 2021). "The six tumour samples with the highest levels of normalized Erbb2 expression were from the six high-amplified tumours, while the three samples with the lowest levels of Erbb2 expression were from the three not/low-amplified tumours." (PMID 34003256, 2021). "We found that KIF11, ERBB2, PI3K, AKT and phosphorylated AKT protein were downregulated after KIF11 siRNA transfection, whereas transfection of ERBB2 plasmids could partially restore this reduction in KIF11 knockdown tumor cells." (PMID 33613109, 2021).
tumor (continued). "We found that the presence of ERBB2 focal amplifications may be relevant to the UICC tumor stage but not to other clinicopathological variables." (PMID 34764264, 2021). "Interestingly, a patient with leptomeningeal metastasis had ERBB2 amplification detected in their CSF but not in their primary tumor tissue." (PMID 34952628, 2021). "In contrast, when NeuNT was knocked into the endogenous Erbb2 locus, and therefore expressed under the control of the endogenous promoter, MMTV-Cre-dependent activation of expression resulted in mammary hyperplasia and the formation of focal tumours after a long latency (over 1 year)." (PMID 34003256, 2021). "One parous tumour showed no ERBB2 staining; in one virgin tumour, staining was punctate within the cytoplasm; in two virgin tumours, weak membrane staining could be seen." (PMID 34003256, 2021). "Interestingly, FIP200 protein was increased by at least 40% by ERBB2 overexpression but reduced by 80% by ERBB2 knockout, although its mRNA level is not significantly affected by ERBB2 expression in patient tumor tissues." (PMID 33801244, 2021). "To test whether ERBB2 amplification pre-existed in the original patient sample from which OCI-C5x was derived, we performed FISH analysis on histology section of the original primary tumor (ovary primary site)." (PMID 33199705, 2020). "In P15 and P25, ERBB2 TMD mutation was identified in CSF and/or plasma but not in tumor tissue." (PMID 32478891, 2020). "However, expression levels were consistently low, not allowing detection of ERBB2 by standard IHC in all tumor-targeted organs." (PMID 33193388, 2020). "Clinically, BC is classified based on the initial morphological assessment of the tumor (type, size, grade, lymph node status), and more recently, on the basis of the expression of receptors of estrogen (ER), progesterone (PR) and human epidermal growth factor 2 (ERBB2/HER2)." (PMID 33168853, 2020). "Furthermore, immune cell engraftment did not lead to severe CRS or xGVHD, but enhanced graft-vs.-tumor effects toward ERBB2-expressing RMS cells." (PMID 33193388, 2020). "Eighteen patients had biopsied tumor tissue and matched plasma at BL, among which a significant concordance of 94.4% (17/18) was achieved, verifying that plasma ERBB2 could be used as an alternative method for the screening of HER2‐targeted population." (PMID 33377634, 2020). "Down-stream analysis suggests the oncogenic effect of ORMDL3 may be an artefact by its nearby oncogene ERBB2 amplification, while its tumor suppressor role cannot be ruled out." (PMID 30621577, 2019). "C, The Her2-negative (Her2–) and Her2-positive tumours (Her2+) were compared to ERBB2 expression." (PMID 31174485, 2019). "In particular, higher ERBB2 incidence and CN gains were observed in GC and CRC patients in the absence of other oncogenic alterations, indicating that HER2 may be the dominant driver of tumor proliferation in those settings." (PMID 31019892, 2019). "Additionally, it was not possible to perform the IHC of the ECD of the ERBB2 protein on these FMTs due to the lack of tumor samples." (PMID 31301170, 2019). "Historically, ERBB2 gene amplification and protein overexpression in tumor biopsy material, as measured by in situ hybridization (ISH) or immunohistochemistry (IHC), has been used to select patients most likely to benefit from HER2-based therapeutic strategies." (PMID 31019892, 2019). "Notably, in our model, tumor development only occurred in the presence of the ERBB2 mutants but not upon overexpression of the WT human ERBB2, further substantiating the notion that mutant ERBB2 is a more potent cancer driver than overexpression of WT ERBB2." (PMID 31795490, 2019). "Furthermore, we found that gene expression of INPP4B, CDK1, and ERBB2 was statistically significantly connected with patient survival in the same manner as the commonly used reference genes ESR1 (for ER status) and MKI67 (for tumor grade or proliferation)." (PMID 31315058, 2019).
tumor (continued). "However, four additional GS that are not directly associated with proliferation but rather represent growth factor signalling pathways were significantly higher in non-responder tumours: ERBB2-GS, IGF1-GS, STAT1-GS, GDNF-GS." (PMID 31892336, 2019). "Because of the significant correlation found between high ERBB1/ERBB2 levels in MTCs and extrathyroidal growth, the detection of ERBB1 and ERBB2 expression suggests that the two oncoproteins may be involved in the tumor proliferative responses and/or in the differentiation of parafollicular C-cells." (PMID 29642647, 2018). "Furthermore, after three days of co-culture (mean 3 days; range 2 – 4 days, n = 3), no tumor cells remained in the presence of ErbB2-CAR CIK cells." (PMID 29029499, 2017). "ERBB2 amplified tumours are a biologically non-homogeneous subgroup of breast cancers." (PMID 28300085, 2017). "Subsequent measurement of tumor biomarker mRNA expression to detect conversion revealed significant decreases in ESR1 and PGR mRNA and MKI67 upregulation (all p < 0.001) in MT compared to PT of all tumor subtypes and ERBB2 upregulation in MT from triple-negative PT patients (p = 0.023)." (PMID 28881657, 2017). "ErbB2 activation is dependent on ErbB2 homodimers or heterodimers with other ErbB family members (ErbB1, 3, 4), which could stimulate constitutive phosphorylation of ErbB2 and initiate the main downstream PI3K/AKT pathway and MAPK pathway, culminating in tumor growth." (PMID 28881779, 2017). "Importantly, this alteration was observed only in tumours that also presented ERBB2 amplification (58/67; 86%); thus, none of the 459 HER2-negative cases was identified as harbouring GSDMB amplification." (PMID 27462779, 2016). "We therefore evaluated whether EGFR, ASAP1, ERBB2 and ERBB4, which signal downstream after ligation of EGF, and which show aberrant expression in several other invasive cancers, would also predict HBL tumor invasiveness." (PMID 27910913, 2016). "Furthermore, multiple receptors interacting with different S100 proteins or S100A8/A9 heterodimers are expressed by both tumor cells and TAMs (SCARA/B, CD36), preferentially by TAMs (AGER, MSR1, TLR4) or by tumor cells (ERBB2), pointing to extensive functional interactions between both cell types." (PMID 27215396, 2016). "Moreover, we and others showed that even the ErbB3 depletion by siRNA was not enough to elicit an apoptotic response in ErbB2-dependent tumours, although it potently inhibited proliferation of tumour cells." (PMID 27255951, 2016). "This suggests, at least anecdotally, that ERBB2 activating mutations do not cause intrinsic endocrine therapy resistance, with high on-AI-treatment Ki67 values that were noted when studying HER2 amplified ER+ tumours in the neoadjuvant endocrine setting." (PMID 27502118, 2016). "In addition to EGFR, the levels of mRNA encoding for the other members of the ErbB family, including ErbB2 and ErbB3, showed a decrease rather than an increase in all resistant tumor cell lines." (PMID 27248176, 2016). "In fact, ErbB2 signaling in non-amplified ErbB2 cells may be abrogated more efficiently than in tumor cells, given the lower amount of ErbB2 copies." (PMID 27596216, 2016). "Blockade of ErbB2/3 by the biparatopic DARPin consistently attenuated Src activity; conversely, the inhibition of Src alone or in combination with trastuzumab does not trigger apoptosis in the 3D tumour model and does not induce PARP cleavage." (PMID 27255951, 2016). "In addition to driving TNBC tumor formation, BRCA1-IRIS overexpression drives their intrinsic and acquired paclitaxel resistance, partly by activating autocrine signaling loops EGF/EGFR-ErbB2 and NRG1/ErbB2-ErbB3." (PMID 25583261, 2015).